EPHA2 (EPH receptor A2)
Diseases named in the same sentence as EPHA2 in open-access papers (continued):
Sharing a sentence is not in itself a finding about the gene and the disease.
ischemic cardiomyopathy (1 paper, 2018). Ischemic cardiomyopathy is a cardiomyopathy in which a weakness in the muscle of the heart due to inadequate oxygen delivery to the myocardium with coronary artery disease being the most common cause. "The most significantly up- and downregulated RTKs were ROR1 and EPHA2, respectively, when ischemic cardiomyopathy was compared to normal heart." (PMID 30342492, 2018). "Interestingly, EPHA2 has been shown to have cardioprotective potential in mouse models of myocardial ischemia and ischemic cardiomyopathy." (PMID 30342492, 2018).
kidney cancer (1 paper, 2020). Primary or metastatic malignant neoplasm involving the kidney. "Knockdown of YB1 and EphA2 increases the sensitivity of SUN-resistant kidney cancer cells to SUN treatment." (PMID 32814829, 2020). "ALW effectively inhibited the growth of SUN-resistant and parental kidney cancer cells, and the inhibitory effect on SUN-resistant cells (high EphA2) was more obvious." (PMID 32814829, 2020).
lentivirus infection (1 paper, 2020). Virus diseases caused by the Lentivirus genus. "EphA2 knockdown was induced in HUVECs by shRNA lentivirus infection with EphA2-RNAi, and bulk RNA-seq assay was performed." (PMID 33510642, 2020).
liver dysfunction (1 paper, 2023).
metastatic colorectal cancer (1 paper, 2021). "A 2013 study on 226 patients with metastatic colorectal cancer (mCRC) treated with cetuximab showed that high EphA2 mRNA receptor expression was an independent prognostic factor for poor outcome while low levels of the EphA2 mRNA were associated with objective response (OR) to cetuximab." (PMID 33572284, 2021).
Nance-Horan syndrome (1 paper, 2012). A syndrome characterized by the association in male patients of congenital cataracts with microcornea, dental anomalies and facial dysmorphism. "Mutations in the genes associated with intercellular contacts, such as Nance-Horan Syndrome (NHS) and Ephrin type A receptor-2 (EPHA2), are other recognized causes of congenital cataract." (PMID 23288986, 2012).
osteoarthritis (1 paper, 2024). A noninflammatory degenerative joint disease occurring chiefly in older persons, characterized by degeneration of the articular cartilage, hypertrophy of bone at the margins and changes in the synovial membrane. "Data mining of transcriptomic datasets identified EPHA2, a receptor tyrosine kinase associated with cancer, as being linked to both inflammation and endochondral ossification in osteoarthritis." (PMID 39717596, 2024). "We then evaluated the effect of EPHA2 inhibition using the tyrosine kinase inhibitor ALW-II-41-27 in cultured human chondrocytes from individuals with osteoarthritis, demonstrating significant reductions in both inflammation and hypertrophy." (PMID 39717596, 2024).
osteoporosis (1 paper, 2023). A condition of reduced bone mass, with decreased cortical thickness and a decrease in the number and size of the trabeculae of cancellous bone (but normal chemical composition), resulting in increased fracture incidence. "We believe that EphA2 overexpression on exosomes is an effective biological vector for targeted inhibition of osteoclasts to help postmenopausal osteoporosis patients preserve bone mass while avoiding the side effects of bisphosphonates." (PMID 37957146, 2023).
Ovarian cyst (1 paper, 2006). The presence of one or more cysts of the ovary. "Hence EphA1, EphA2, EphB2, EphB3, EphB6, ephrin A1, ephrin A5 and ephrin B1 were selected for further analysis in an additional fourteen tumor samples, one ovarian cyst and one ovarian adenoma." (PMID 16737551, 2006).
parasite (1 paper, 2018). "We analyzed whether EphA2 surface expression correlates with parasite infection rates, using the Hepa1-6 cell model and PbGFP sporozoites." (PMID 29975762, 2018).
pharyngeal-carcinoma (1 paper, 2021). "For instance, reintroduction of pY772A EphA2 in EphA2 knock-down naso-pharyngeal-carcinoma (NPC) cells increased cell proliferation, anchorage-independent growth in vitro and tumor growth in vivo." (PMID 33572284, 2021).
post-traumatic stress disorder (1 paper, 2025). An anxiety disorder precipitated by an experience of intense fear or horror while exposed to a traumatic (especially life-threatening) event. "TBI is a risk factor for post-traumatic stress disorder (PTSD), and multiple single-nucleotide variants of EPHA2 are linked to PTSD." (PMID 40498000, 2025).
postmenopausal osteoporosis (1 paper, 2023). Metabolic disorder associated with fractures of the femoral neck, vertebrae, and distal forearm. "In summary, miR-210 promotes osteogenic differentiation and inhibits adipogenic differentiation of BMSCs by down-regulation of EPHA2 expression, thereby alleviating postmenopausal osteoporosis." (PMID 37904187, 2023).
pregnancy (1 paper, 2018). The status during which female mammals carry their developing young (EMBRYOS or FETUSES) in utero before birth, beginning from FERTILIZATION to BIRTH. "With respect to the protein level, a significantly higher ratio of EphA2 over Pho-EphA2 was shown in women with tubal pregnancy (P < 0.05)." (PMID 30176889, 2018). "As a similar molecular mode may exist between uterine implantation and tubal implantation, it is reasonable to expect EphA2 involvement in tubal pregnancy." (PMID 30176889, 2018). "The changes of EphA2 and its activated form, phosphorylated-EphA2 (Pho-EphA2), in the Fallopian tube epithelium from non-pregnant women (n = 12) and women with tubal pregnancy (n = 14) were compared by quantitative RT-PCR and western blot assay." (PMID 30176889, 2018).
promyelocytic leukemia (1 paper, 2017). "Moreover, EphA2 and EphA4 expression was induced, and ephrin-A4 expression was upregulated, in a human promyelocytic leukemia cell line, HL60, along with monocyte differentiation toward the classical CD14++CD16− monocyte subset." (PMID 28851287, 2017).
prostate (1 paper, 2020). "In accord with our results obtained via prazosin treatment, an earlier study showed that a quinazoline-like small molecule, doxazosin, activates EphA2 in a ligand-dependent manner and suppresses tumor cell metastasis in prostate cancer." (PMID 32203105, 2020).
pulmonary edema (1 paper, 2021). Accumulation of fluid in the lung tissues causing disturbance of the gas exchange that may lead to respiratory failure. "Secondly, in the first three patients treated with EphA2-directed CAR-T cells, G2 pulmonary edema was reported, which could be an on-target, off-tumor effect considering that EphA2 is expressed in the adult lung epithelium." (PMID 34831119, 2021).
renal fibrosis (1 paper, 2016). A final common manifestation of a wide variety of chronic kidney diseases characterized by glomerulosclerosis and tubulointerstitial fibrosis. "The list of genes includes Fblim1, Epha2, Wisp1, Parvg, Madcam1, Mybpc2, Cdh3, Gpr56, Troap, Pstpip1, Pcdh8, Nlgn2 and Mfap4, genes that based on Pubmed and Kidney and Urinary Pathway Knowledge Base12 searches have not been previously associated with renal fibrosis." (PMID 27189340, 2016).
retinal diseases (1 paper, 2021). "EphrinA1, ephrinA4, ephrinA5, EphA2, EphA7, ephrinB2, EphB3, and EphB4 seem to be the most important in the context of retinal diseases." (PMID 34201393, 2021).
spina bifida (1 paper, 2022). A congenital neural tube defect in which vertebrae are not fully formed. "We reported that three out of seven spina bifida probands and three out of thirteen family members carried a variant in either EPHA2 (rs147977279), EPHB6 (rs780569137) or EFNB1 (rs772228172)." (PMID 35741713, 2022).
staphylococcal infection (1 paper, 2019). An infection caused by Staphylococcus. "We confirmed the importance of EPHA2 for staphylococcal infection in an EPHA2-knock-out cell line." (PMID 30890742, 2019).
teratoma (1 paper, 2024). A non-seminomatous germ cell tumor characterized by the presence of various tissues which correspond to the different germinal layers (endoderm, mesoderm, and ectoderm). "However, the removal of EPHA2+ cells by EPHA2-MACS significantly mitigated teratoma formation, indicating EPHA2 as a viable antigen for identifying teratoma-forming cells within differentiated cell populations." (PMID 38811016, 2024).
uterine carcinoma (1 paper, 2022). A carcinoma involving a uterus. "Notably, the phosphorylation status of EPHA2 Ser897 is a key determinant of therapeutic response to dasatinib in uterine carcinoma cells." (PMID 36297233, 2022).
tumor (551 papers, 2003 to 2026). "Alternatively, our orthotopic mouse study showed that EphA2 knockdown reduced the apoptosis resistance of tumor cells, decreased the overall tumor cell number, and lowered the tumor weight, further confirming the cancer-associated functions of EphA2." (PMID 41440001, 2025). "Although EphA2 is implicated in tumor growth and metastasis of many types of solid cancers through ligand-independent signaling, it can also suppress cell growth via ligand-dependent signaling through ephrin-A1, its primary binding partner." (PMID 40867322, 2025). "Tumor-intrinsic EphA2 has been shown to have both tumor-promoting and tumor-suppressing effects in the presence of KRAS mutations." (PMID 40867322, 2025). "In this process, reduced FAK/RhoA signaling, a downstream effector of EphA2, was associated with attenuated tumor progression in RCC." (PMID 41440001, 2025). "Given that EphA2 and ephrinA1 play an important role in tumor angiogenesis, Shao and co-workers (2013), studied the association of EphA2 and ephrinA1 in AdCC." (PMID 40421081, 2025). "Analysis of lung tumor infiltrates via flow cytometry revealed decreased natural killer and T cells in the EphA2-overexpressing tumors, as well as increased myeloid populations, including tumor-associated macrophages (TAMs)." (PMID 40867322, 2025). "Although it has been shown that Zmynd11 regulates RNA polymerase II elongation in tumor, we observed that Zmynd11 deficiency reduced the binding of RNA Polymerase II at Epha2 promoter in eNPCs and brain samples." (PMID 40281637, 2025). "Third, EphA2 is known to be expressed on tumor-associated vasculature, where it plays a role in angiogenesis and vascular remodeling." (PMID 40225586, 2025). "Loss of function experiments involving EphA2 demonstrated a substantial reduction in tumor growth, angiogenesis, and lung metastasis in EphA2 knockout female mice." (PMID 38612592, 2024). "Considering EphA2 prognostic value, EphA2 expression correlated with risk factor and poor overall survival (OS) in 10 out of 33 neoplasia." (PMID 39596256, 2024). "A human adenovirus vector encoding EphrinA1-Fc, a ligand of tyrosine kinase receptor EphA2 overexpressed in BC which can inhibit tumor progression, and one expressing Flt3L were evaluated in small (30-50mm3) EphA2 overexpressing MT1A2 tumors in a murine model." (PMID 38803496, 2024). "Downregulation of the tumor suppressive angiocrine factor Slit2 and upregulation of its inhibitor receptor EphA2 on tumor-associated ECs promote tumor proliferation and motility." (PMID 38426109, 2024). "It was observed that the overexpression of EPHA2 is associated with low survival rates and tumour recurrence." (PMID 38247816, 2024). "In another study, CAR-T cells targeting EphA2 demonstrated anti-tumour activation linked to upregulation of CXCR-1/2 and appropriate interferon-γ (IFN-γ) production." (PMID 38660136, 2024). "At the cellular level, the deregulated expression of EPHA2 was linked to the promotion of tumour aggressiveness, invasion, and metastasis." (PMID 38247816, 2024). "EphA2 expression was significantly associated with patient age, while EphA4 and EphA5 with tumor proliferative capacity." (PMID 39839790, 2024). "Another member of the Eph receptors, EphA2, has been linked to increased susceptibility to chemical carcinogen-induced skin cancer, as well as elevated tumor cell proliferation and phosphorylation of Erk when deficient in mice." (PMID 38811954, 2024). "Ephrin-dependent stimulation of EphA2 in several tumour cell lines causes rapid dephosphorylation of Akt T308 and S473, most probably via control of a phosphatase, which in turn inhibits mTORC1 and reduces cellular proliferation and motility." (PMID 36830852, 2023). "EphA2 also amplifies the oncogenic signalling of the RTK erbB2 (HER2), and the loss of EphA2 in the mammary epithelium of mice slowed down tumour development and metastasis." (PMID 36830852, 2023).
tumor (continued). "EphA2 is overexpressed in different cancers and has been associated with tumor malignancy and poor prognosis." (PMID 37530973, 2023). "EphA2 and ephrin-A1 are expressed in tumours and associated vessels, with mouse models indicating that EphA2 expression in vessels is important for efficient angiogenesis." (PMID 37760615, 2023). "This EphA2 overexpression is associated with tumor metastasis and poor patient survival and consequently linked to a highly aggressive cancer phenotype." (PMID 36142306, 2022). "The upregulation of EphA2 was reported in several studies related to breast, prostate, lung, pancreas, and most importantly, ovarian cancer, and causes tumor invasion, metastasis and angiogenesis." (PMID 35456698, 2022). "Intriguingly, mice that are EphA2-deficient, or cancer cells with EphA2 knockdown, exhibited reduced tumor development, angiogenesis, and metastasis." (PMID 36142306, 2022). "The involvement of EphA2 in Vδ1-mediated tumor cell lysis was demonstrated by reduced susceptibility to killing by EphA2 blocking." (PMID 35747139, 2022). "Eph receptors have been implicated in tumour formation and progression, with EphA2 being the most frequently perturbed Eph receptor associated with cancer development and progression, including both prostate and breast cancer." (PMID 35869144, 2022). "EphA2 was also abnormally highly expressed in a variety of tumors and found to be associated with tumor cell proliferation and migration." (PMID 33712565, 2021). "We observed a 2.5‐fold decrease in IL‐6 protein levels in 4T1.ΔC‐conditioned medium versus control (p < 0.05), confirming reduced expression in EphA2 loss of function tumor cells." (PMID 33869989, 2021). "BT5528 comprises a bicyclic peptide targeting the tumor antigen EphA2 linked to a cytotoxin (monomethyl auristatin E) via a tumor microenvironment cleavable linker." (PMID 34641586, 2021). "Adding further to the multifaceted role of EphA2 in NSCLC, it was reported that EphA2 associates with PLCγ1 into a signaling circuit that influenced tumor cell growth." (PMID 33671073, 2021). "This repulsive event apically extrudes the Ras-mutated cell from the epithelium, thus enacting a tumour-suppressive role for EphA2." (PMID 34819513, 2021). "In keeping with a tumor-suppressive role for ligand-bound EphA2, forward signaling elicited by ephrin-A ligands from normal cells on EphA2 expressing, RasV12 positive cells caused repulsion and segregation of the transformed cells." (PMID 33572284, 2021). "EPHA2 overexpression was positively linked to tumor size, higher histological grade of tumors, peritumoral edema levels, and poor patients prognosis." (PMID 34445116, 2021). "Tumor DNA analysis revealed (a) an EPHA2 G391R variant, which causes continuous activation of EPHA2, with increased phosphorylation of Src, cortactin, and p130." (PMID 33466719, 2021). "We therefore developed a multimodal oncolytic herpes simplex virus (oHSV) that expresses ephrin A2 (EphA2), a shared tumor-associated antigen (TAA) expressed by many tumors to improve immune-mediated antitumor activity." (PMID 34599026, 2021). "Xenograft mouse models and cell experiments in vitro showed that the loss of EphA2-SE attenuates tumor progression." (PMID 33712565, 2021). "In summary, we evaluated Vδ1 γδ T-cell cytotoxicity against tumor cells and found consistently that EphA2 expressed on cancer cells show susceptibility to cell lysis by tumor-reactive Vδ1 T cells." (PMID 34691070, 2021). "Both EphA2 and EpCAM are tumor-associated antigens that are overexpressed in patients with esophageal squamous cell carcinoma but are not tumor-specific antigens." (PMID 34386424, 2021). "EphA2 loss of function in tumor cells impaired osteoclast progenitor differentiation in coculture, which is mediated, at least in part, by reduced expression of IL‐6." (PMID 33869989, 2021).